NLRP3 (NLR family pyrin domain containing 3)
Diseases named in the same sentence as NLRP3 in open-access papers (continued):
Sharing a sentence is not in itself a finding about the gene and the disease.
Cognitive impairment (continued). "Furthermore, knockdown of NLRP3 in astrocytes not only reduced GABA production in astrocytes, but also increased neuronal survival and improved neuronal function, thereby ameliorating not only TF-induced impulse-like behaviors but also cognitive impairment." (PMID 37434240, 2023). "However, the interaction between NLRP3 inflammasomes and mitophagy in the sevoflurane-induced cognitive impairment had not been fully clarified." (PMID 36696410, 2023). "Additionally, previous studies found that the abundance of pro-inflammatory Escherichia/Shigella in stool was higher in patients with cognitive impairment and brain amyloidosis than in the control group, and was positively related to the level of IL-1β, CXCL2 and NLRP3 inflammasome." (PMID 36405958, 2022). "With this regard, expressions of NLRP3, GSDMD-NT, and cleaved caspase-1 were augmented in the brain of septic mice, and the upregulation of NLRP3, caspase-1, and gasdermin-D in the hippocampus resulted in the cognitive deficits in the mice model of SAE by inducing pyroptosis." (PMID 35832175, 2022). "Injection of Ac-YVAD-cmk (an NLRP3/caspase 1 inhibitor) prior to anesthesia did improve cognitive impairments and prevent hippocampal inflammation in aged mice, but not in young mice, which was possibly due to the attenuation of isoflurane-triggered NLRP3 inflammasome." (PMID 36503642, 2022). "Therefore, NLRP3 inhibitors and AST-120 may be effective therapies for CKD-induced cognitive impairment." (PMID 34572437, 2021). "The lack of experimental data on neuron- or microglial-specific NLRP3 knockout makes it difficult to draw definitive conclusions regarding the mechanisms by which p-tau overexpression leads to cognitive impairment, which is worthy of further research in the future." (PMID 34539383, 2021). "Taken together, our results demonstrate that the NLRP3 inflammasome participates in the pathogenesis of cognitive deficits in EAE animals, and that pretreatment with an NLRP3 inhibitor could significantly ameliorate EAE-related cognitive deficits and reduce the hippocampal pathology." (PMID 32415059, 2020). "Furthermore, it was recently demonstrated to ameliorate the postoperative cognitive impairment induced by surgery/sevoflurane, possibly through its inhibitory effect on the activation of the NLR family pyrin domain containing 3 (NLRP3) inflammasome in the hippocampus." (PMID 32549398, 2020). "Therefore, inflammasome NLRP3, ASC, caspase-1, GSDM-D, IL-1β, and IL-18 are key signaling molecules for inflammation and cell pyroptosis and are involved in the process of CI and other cognitive disorders." (PMID 31781266, 2019). "However, the cellular basis for cognitive impairment is still not fully understood, and effective pharmacologic agents targeting the NLRP3 inflammasome during GA are lacking." (PMID 30524241, 2018). "To ascertain whether treatment with A. muciniphila prevented cognitive impairment by inhibiting hippocampal NLRP3‐mediated neuroinflammation activation, we assessed the expression levels of ASC, Cleaved Caspase 1, IL‐18, NF‐κB, p‐NF‐κB and NLRP3 in the hippocampus after the behavioral study." (PMID 40050112, 2025). "To testify this hypothesis, we employed a selective small-molecular inhibitor (MCC950) of the NLRP3 inflammasome signaling to inhibit inflammasome activation and revealed that MCC950 treatment significantly prevented Aβ deposition and alleviated the cognitive impairments induced by HSV-1 infection." (PMID 39026249, 2024). "Not only the pyroptosis inhibiter, necrosulfonamide (NSA), could improve cognitive impairment via suppressing pyroptosis, but also the ROS scavenger, N-acetylcysteine (NAC), could ameliorate POCD by reducing the level of ROS and pyroptosis through NLRP3 inflammasome pathway." (PMID 37332874, 2023).
Cognitive impairment (continued). "TBI has been well documented to promote both priming and activation of the NLRP3 inflammasome through several factors, while the role of the NLRP3 inflammasome in the late phase of TBI (for mice > 4 w), especially in the development of TBI-induced cognitive impairment, remains unclear." (PMID 34666797, 2021). "In this study, the alteration of NLRP3 levels was not obvious, but the NLRP3 inflammasome was activated 7 m post injection, and cognitive impairment appeared, indicating that it may be a major contributor to the elevation in HMGB1 and abnormal cognition resulting from tau overexpression." (PMID 34539383, 2021). "However, there is no research on NLRP3 inflammasome in MS-related cognitive deficits." (PMID 32415059, 2020). "In the present study, we hypothesize that NLRP3 inflammasome-dependent pyroptosis is involved in the mechanism of isoflurane-induced cognitive impairment in aged mice and that inhibiting the NLRP3 inflammasome with MCC950 may ameliorate isoflurane-induced pyroptosis and cognitive impairment." (PMID 30524241, 2018). "In individuals with mild cognitive impairment (MCI), NLRP3 expression was elevated, but PYCARD or caspase 1 was not, indicating that functional inflammasomes were not assembled." (PMID 40538660, 2025). "Moreover, treatment with MCC950, a specific inhibitor of the NLRP3 that inhibits NLRP3-induced ASC oligomerization, promoted non-phlogistic clearance of β-amyloid and ameliorated cognitive impairment." (PMID 33499208, 2021).
Parkinson disease (234 papers, 2016 to 2026). A progressive degenerative disorder of the central nervous system characterized by loss of dopamine producing neurons in the substantia nigra and the presence of Lewy bodies in the substantia nigra and locus coeruleus. "It is necessary to point out that an increase in the functioning of the NLRP3 inflammasome causes a deficit in microglial autophagy in Parkinson’s disease, leading to a change to a neurotoxic condition in microglia." (PMID 39861194, 2025). "In Parkinson’s disease, microglia modulate α-synuclein clearance but sustain neuroinflammation via NLRP3 inflammasome activation, driving dopaminergic neuron loss." (PMID 40699743, 2025). "This study aimed to investigate the role and underlying mechanism of DJ-1 in regulating NLRP3 inflammasome-mediated neuroinflammation during Parkinson’s disease." (PMID 40990010, 2025). "Activation of the NLRP3-inflammasome has been implicated in Parkinson's disease based on in vitro and in vivo studies." (PMID 37886468, 2024). "In this study, we conducted analyses of common and rare variants in NLRP3-inflammasome related genes in Parkinson's disease cohorts." (PMID 37886468, 2024). "Abnormal activation of NLRP3 inflammasomes can exacerbate inflammation-driven diseases, such as Cryopyrin-associated cyclical syndromes, Alzheimer’s disease, Parkinson’s disease, rheumatoid arthritis, and cancer." (PMID 38172822, 2024). "α-Synuclein (αSyn) in microglia mediates NLRP3 inflammasome activation to induce IL-1β secretion, and pyroptosis induced by αSyn damages dopamine neurons and causes Parkinson's disease." (PMID 36378463, 2023). "In contrast, rare mutations in the NLRP3 inflammasome have been associated with a decreased risk of Parkinson’s disease." (PMID 34775541, 2022). "Dysregulation of the inflammasome NLRP3 has been associated with the onset and progression of a wide range of neurological conditions such as Alzheimer’s and Parkinson’s diseases, among others." (PMID 35803999, 2022). "Dopamine promotes the autophagic degradation of NLRP3 inflammasomes by enhancing the K48-linked ubiquitination of NLRP3, thereby playing a protective role against Parkinson's disease, neuritis, and peritonitis." (PMID 32003754, 2020). "Activity of the proinflammatory NLRP3 inflammasome is implicated in Alzheimer’s and Parkinson’s disease and our recent studies in patients suggest that dopaminergic neurons within the degenerating mesencephalon express NLRP3 throughout the progression of PD." (PMID 32680528, 2020). "Here, we report that the Parkinson’s disease-associated mitochondrial serine protease HtrA2 restricts the activation of ASC-dependent NLRP3 and AIM2 inflammasomes, in a protease activity-dependent manner." (PMID 29855523, 2018). "α-Synuclein (α-Syn), a pathological hallmark of Parkinson’s disease (PD), has been recognized to induce the production of interleukin-1β in a process that depends, at least in vitro, on nod-like receptor protein 3 (NLRP3) inflammasome in monocytes." (PMID 27084336, 2016). "Moreover, NF-κB regulates inflammasome activity, which in turn triggers the NLRP3 inflammasome and causes Parkinson’s disease patients to release NLRP3-dependent inflammatory cytokines." (PMID 40509336, 2025). "Similarly, in Parkinson’s disease, the presence of α-synuclein aggregates is associated with the activation of NLRP3, underscoring the role of the inflammasome in the inflammatory environment surrounding pathological protein aggregation." (PMID 40075143, 2025). "MCC950 and miRNA-7 inhibitors, by suppressing the activation of the NLRP3 inflammasome within microglial cells, can alleviate neuroinflammation and neuronal damage associated with Parkinson’s disease, offering new potential therapeutic targets for the treatment of PD." (PMID 40552323, 2025). "NLRP3 inflammasome activation is closely associated with Parkinson’s disease pathogenesis." (PMID 37681916, 2023).
Parkinson disease (continued). "Additionally, a-synuclein, which is the underlying aggregate causing Parkinson ́s disease, significantly enhanced inflammasome activation, which was completely dependent on NLRP3." (PMID 35626754, 2022). "The NOD-, LRR-, and pyrin domain-containing protein 3 (NLRP3) inflammasome plays an important role in the canonical pyroptosis pathway, which is associated with neurodegenerative diseases, such as AD, Parkinson’s disease, and epilepsy, and is a pivotal role in PNDs." (PMID 36688154, 2022). "Furthermore, the NLRP3 inflammasome has been linked to chronic inflammatory disorders based on protein aggregation such as Alzheimer's and Parkinson's diseases." (PMID 30761127, 2019). "Therefore, targeting the NLRP3 inflammasome and its associated molecules could be a therapeutic strategy for neuroinflammatory diseases, including Parkinson’s disease." (PMID 39058145, 2024). "Aberrant and/or excessive NLRP3 inflammasome activation has been implicated in several conditions, including diabetes, cryopyrin-associated periodic syndromes, neurodegenerative diseases such as Parkinson’s and Alzheimer’s disease, as well as both ischemic and hemorrhagic stroke." (PMID 38327788, 2024). "Recent study showed that NLRP3 gene deficiency in mice altered the gut microbiota composition and affected both mood-related behaviors and locomotor activities, whether this is also true in Parkinson’s disease has yet to be studied." (PMID 36313019, 2022). "Besides, NLRP3 inflammasome activation may aggravate dopaminergic neuronal loss in Parkinson’s disease." (PMID 34775541, 2022). "Given the intertwined roles of SIRT1, Nrf2, and NLRP3 in regulating neuroprotection, oxidative stress responses, and inflammasome-mediated inflammation, evaluating these pathways together may provide deeper mechanistic insight into the redox–inflammatory imbalance underlying Parkinson’s disease." (PMID 41601525, 2026). "In Parkinson’s disease, folate deficiency and hyperhomocysteinemia exacerbate motor deficits and dopaminergic neurodegeneration via oxidative stress, mitochondrial dysfunction, and NLRP3-mediated inflammation and combined folate and vitamin B12 supplementation may reduce levodopa-associated risks." (PMID 42043709, 2026). "The NLRP3 inflammasome is upregulated in microglia from Parkinson's disease patients and activated by oxidative stress and α-synuclein aggregates, triggering the release of pro-inflammatory mediators that contribute to neuroinflammation and neuronal death." (PMID 41099134, 2026). "MCC950, the first described specific NLRP3 inhibitor, has shown promise in Parkinson's disease models but is limited by suboptimal pharmacokinetics and safety, hindering its clinical development." (PMID 41099134, 2026). "Increasing evidence indicates that excessive microglial inflammasome activation contributes to neurodegeneration, and the NLRP3 inflammasome inhibition is being explored as a therapeutic strategy in conditions like Alzheimer’s and Parkinson’s disease." (PMID 41596340, 2026). "Pramipexole inhibited astrocytic NLRP3 inflammasome activation via Drd3-dependent autophagy in a mouse model of Parkinson’s disease." (PMID 41516359, 2026). "Key signaling pathways involved in inflammasome activation in microglial cells during Parkinson’s disease progression include TLRs/NF-κB/NLRP3, TLR/NLRP3/Caspase-1, and NF-κB/AP-1/Nrf2." (PMID 40552323, 2025). "QijiShujiang granules alleviate the dopaminergic neuronal injury of Parkinson’s disease by inhibiting the NLRP3/caspase-1 pathway." (PMID 40305201, 2025). "NLRP3 activation is also involved in other neurodegenerative and neurodevelopmental conditions, including Parkinson’s disease, multiple sclerosis (MS), and autism spectrum disorder (ASD)." (PMID 41162989, 2025). "NLRP3 inflammasomes-mediated proinflammatory response and mitochondrial dysfunction play a critical role in the etiology and pathogenesis of Parkinson's disease." (PMID 39096445, 2025).
Parkinson disease (continued). "MicroRNA-7 alleviates Parkinson’s disease-related neuroinflammation and dopaminergic neuronal damage by inhibiting microglial NLRP3 inflammasome activation, offering a potential novel therapeutic target." (PMID 40552323, 2025). "For example, LncRNA KCNQ1OT1 promotes NLRP3 inflammasome activation in Parkinson’s disease by regulating the pri-miR-186/mature miR-186/NLRP3 axis." (PMID 40652273, 2025). "This section breaks down the molecular relationship between Nrf2-Keap1 signaling and NLRP3 inflammasome activity in Parkinson’s disease into multiple subsections to provide a more comprehensive and understandable picture." (PMID 41261343, 2025). "In α-syn contexts relevant to Parkinson’s disease, HXT reduces the TLR4/MyD88 cascade that drives NF-κB/MAPK signalling and NLRP3 inflammasome activation, a central pathogenic axis produced during Parkinson’s disease." (PMID 41227598, 2025). "Rodent models of HIV associated neurocognitive disorders (HAND), such as Alzheimer’s disease, bipolar disorder, and Parkinson’s, further display NLRP3’s role in brain dysfunction." (PMID 41181331, 2025). "The interaction barrier between mitochondria and lysosomes, along with the pathological interaction of the NLRP3 inflammasome, constitutes a core driving network for the progression of Parkinson’s disease." (PMID 41048372, 2025). "GAS5 has been shown to accelerate Parkinson’s disease (PD) progression by promoting inflammation in microglia through the miR-223-3p/NLRP3 axis." (PMID 39941145, 2025). "Dopamine deficits have been shown to activate NLRP3 in primary human microglia and a mouse model of Parkinson’s disease." (PMID 40234284, 2025). "Activation of the Nrf2-Keap1 pathway can inhibit NLRP3 and act as a protective mechanism in Parkinson’s disease." (PMID 41261343, 2025). "This study identified DJ-1 as a previously underappreciated regulator of the NLRP3 inflammasome in microglia in the context of Parkinson’s disease." (PMID 40990010, 2025). "Selnoflast (RO7486967), formerly named somalix/RG6418/IZD334, an orally potent, selective, and reversible small molecule NLRP3 inflammasome inhibitor, has completed the Phase 1b study in participants with Early Idiopathic Parkinson’s Disease." (PMID 40038816, 2025). "Parkinson’s disease (PD) is a neurodegenerative disease with strong links to mitochondrial dysfunction and NLRP3-drive inflammation." (PMID 40854880, 2025). "Recent studies have shown that NLRP3 is a parkin substrate that drives neurodegeneration in Parkinson's disease." (PMID 39800672, 2025). "Stat3 was reported to be capable of binding to the NLRP3 promoter and enhanced NLRP3 transcription to participate in neuronal pyroptosis, mechanical allodynia, and Parkinson's disease." (PMID 39601144, 2024). "Then it can be confirmed the NLRP3 inflammation suppression play a key function of Safranal in Parkinson’s disease." (PMID 38683404, 2024). "In a TLR4-dependent manner, MPTP activated NLRP3/caspase-1/GSDMD cascade in mouse model of Parkinson’s disease." (PMID 39253076, 2024). "BA results in the remission of neuroinflammation through limiting the NLRP3/caspase-1/GSDMD pathway in mice with Parkinson's disease." (PMID 39662962, 2024). "NLRP3/caspase-1/GSDMD pathway was shown to contribute to neuroinflammation in mouse model of Parkinson’s disease induced by N-methyl-4-phenyl-1,2,3,6-tetrahydropyridine (MPTP)." (PMID 39253076, 2024). "Safranal played a neuroprotective effect on the Parkinson’s disease and its mechanism was related to the inhibition of NLRP3 inflammasome activation." (PMID 38683404, 2024). "This inhibition successfully protected dopamine neurons in the midbrain substantia nigra, suppressing NLRP3 inflammasome-mediated Parkinson's disease development." (PMID 38317229, 2024). "In preclinical models of neurogenerative diseases, such as Alzheimer and Parkinson’s it has been shown that NLRP3 activation deteriorates cognitive and motor function in mice." (PMID 39188718, 2024).